OXT (oxytocin/neurophysin I prepropeptide)
Diseases named in the same sentence as OXT in open-access papers (continued):
Sharing a sentence is not in itself a finding about the gene and the disease.
Anxiety (continued). "It has been reported that the OXT/OXTR signaling pathway plays a role in regulation of a variety of social behaviors as well as ASD etiology and is involved with anxiety-like behaviors." (PMID 35370982, 2022). "OXT and the OXTR are involved in regulation of anxiety, stress, and reward-related behaviors." (PMID 36077337, 2022). "A negative correlation was also found between OXT levels and depression, and the stress scale in the depression anxiety and stress scales (DASS)." (PMID 34805562, 2021). "Although oxytocin (OXT) has been reported to improve object recognition, social recognition, anxiety behavior, and depression-like behavior in specific conditions, previous studies did not explore the impact of OXT in high-fat diet (HFD)-fed mice." (PMID 32719656, 2020). "This suggests that OXT and AVP regulate different types of anxiety." (PMID 31354450, 2019). "Oxytocin (OXT) and arginine-vasopressin (AVP) are two neuropeptides synthesized in the supraoptic nucleus (SON) and paraventricular nucleus (PVN) of the hypothalamus and are related to social interaction, social memory and anxiety in mammals." (PMID 30971895, 2019). "Taken together, our findings are along with the hypothesis that while OXT is primarily engaged in the performance of social behaviors, CRH is greatly involved in the regulation of stress and anxiety." (PMID 30898126, 2019). "The same dose of intracerebroventricular (ICV) injection of OXT did not ameliorate isolation-induced depression and anxiety-related behaviors." (PMID 30158853, 2018). "Recent data have reported a significant negative correlation between plasma OXT levels and symptoms of depression and anxiety, in 25 patients with major depressive disorder." (PMID 22997507, 2012). "In addition to the pro-social and anti-stress effects, OXT reduced anxiety behaviors in animals, acting as an anxiolytic nonapeptide in vivo." (PMID 37153633, 2023). "Not only have animal model studies demonstrated that chronic intranasal dosing with OXT can lead to receptor down-regulation in the forebrain, but it can also result in impaired rather than enhanced social behavior and increased rather than decreased anxiety." (PMID 35214056, 2022). "Since the anxiolytic effect of the OXT is mediated via phosphorylation of ERK1/2, we hypothesize that the attenuated phosphorylation level in OXTR A218T cells accounts, to some extent, for comorbid anxiety found in some cases of ASD." (PMID 34980886, 2022). "Additionally, there is a correspondence between anxiety, suicidal ideation and negative social interactions, and this correlated with salivary OXT levels." (PMID 34805562, 2021). "To test our hypotheses we studied the effects of gestational stress, fluoxetine treatment and environmental enrichment on anxiety (open field test), depression-like behavior (social interaction and sucrose preference, forced swim test), HPA axis function, and OXT in the brain." (PMID 33875712, 2021). "Thirdly, in the current study the anxiety/mood assessments were only made prior to treatment and so we cannot exclude the possibility that a non-specific OXT effect on mood/anxiety might have influenced subjects’ behavior." (PMID 28588469, 2017). "Interestingly, we found that early developmental perturbation of the PT OXT neuronal cluster produced a specific long-term effect on their functionality leading to specific defect in the shoaling behavior, but not in the anxiety-like response." (PMID 28094761, 2017). "Moreover, the observation that ablation of PT OXT neurons did not affect anxiety-like behavior uncouples the contribution of this cluster to social behavior from the general otpa−/− neuroanatomical and behavioral deficits." (PMID 28094761, 2017). "Differences in the activity of the brain OXT systems between selectively bred for high- and low-anxiety related behaviours rats may, at least partially, contribute to the opposing anxiety but not depression-relate behavior." (PMID 22997507, 2012).
Anxiety (continued). "Interestingly, exogenous OXT in lactating rats reduced pMEK1/2 levels without a concomitant effect on anxiety, indicating that OXT receptor activation can lead to recruitment of additional intracellular pathways to modulate MEK activity." (PMID 22615888, 2012). "Moreover, in contrast to virgin and male rats, where acute OXT administration resulted in an increased pMEK/MEK ratio, OXT did not cause further activation of MEK1/2 in lactating rats, and was concomitantly without effect on anxiety-like behaviour." (PMID 22615888, 2012). "In the FST and the EZMT, co-administration of OXT (0.5 μg) with OXTRA (1 μg) into the CeA did not rescue isolation-induced depression and anxiety-related behaviors in the FST and the EZMT, respectively." (PMID 30158853, 2018). "Given the fact that both OXT and PRL are key players during the peripartum period, acting synergistically to regulate maternal care, anxiety, and stress, it is not surprising PRL-R expression is comparably altered during that time." (PMID 24883213, 2014).
autism (77 papers, 2009 to 2025). Persistent deficits in social interaction and communication and interaction as well as a markedly restricted repertoire of activity and interest as well as repetitive patterns of behavior. "For example, some studies found lower plasma OXT associated with autism, depression, and schizophrenia while other studies described higher OXT levels associated with autism and depression." (PMID 31998152, 2019). "Taken together, we demonstrated there was central OXT deficiency in the VPA-induced rat model of autism, and showed evidence that early postnatal OXT treatment had a long-term therapeutic effect on the autistic-like behaviors in VPA rats." (PMID 30356897, 2018). "Polymorphisms in OXT and its receptor are associated with autism risk, and intranasal OXT improves autism symptoms and imaging abnormalities." (PMID 28859103, 2017). "In particular, developmental disruptions of the oxytocin (OXT) system have been implicated in many pathological conditions, including autism and Prader-Willi syndrome, which are associated with impaired responses to stressful, social and metabolic stimuli." (PMID 28094761, 2017). "In a Swedish twin study, the researchers observed an association between OXT rs2770378 and autism-like traits including language impairment and restricted behaviors in females but not males with ASD." (PMID 27242401, 2016). "It is worth mentioning here that FOXP2 protein dramatically down-regulates CNTNAP2, a strong candidate gene for autism, whereas OXT gene encodes the neuropeptide binding the oxytocin receptor (OXTR), another strong candidate gene for autism." (PMID 20885821, 2010). "Recently, impaired OXT function has been implicated in the abnormal social communications seen in certain human psychiatric diseases such as autism and schizophrenia, although a causal role of OXT in specific human behaviors and associated disorders is still to be clearly established." (PMID 29231812, 2017). "Thus, a link between deficient OXT system and autism have been established, and in support of this, OXT knockout mice show reduced social memory, an important behavioral phenotype of autism." (PMID 27964753, 2016). "It has been shown that deficient OXT system is implicated in the development of autism and supplement of OXT in the brain by intranasal administration of OXT increases retention of social cognition in patients with autism." (PMID 27964753, 2016). "As originally put forward by Modahl, a deficit in the OXT system linked to an altered opioid regulation may underline the social deficits in autism." (PMID 25225634, 2014). "Moreover, nasal application of OXT has been associated to improving lactation failure, autism, schizophrenia, and other aberrant social behaviors bypassing the blood-brain barrier via multiple approaches." (PMID 24967304, 2013). "Thus, impairments in the AVP/OXT systems might be associated with aberrant brain morphology and function in autism." (PMID 28258508, 2017). "Interestingly, while dysregulated OXT levels are implicated in autism-spectrum disorders and OXT supplementation may help patients with autism; children with autism also show reduced REMS." (PMID 28367113, 2017). "Peripheral plasma OXT levels and the autism spectrum quotient (AQ) were used for correlation analyses." (PMID 38228703, 2024). "Oxytocin (OXT), a neurotransmitter known for its role in social behavior, has been proposed to modulate certain autism-related symptoms by influencing microglial function and attenuating neuroinflammation." (PMID 39557567, 2024). "Early evidence for the connection between OXTR and autism came from observations that significant changes in plasma oxytocin OXT levels occur in affected patients." (PMID 36835321, 2023). "The outcome also raises questions about the implications of findings related to OXT alterations in the fMRI brain networks of individuals with autism." (PMID 38066793, 2023).
autism (continued). "Marazziti and Vecchia describe, in a recent review, the possible link between OXT and autism, as well as other neuropsychiatric disorders." (PMID 36358953, 2022). "The exact pathways of OXT effects in autism, cardiovascular diseases and obesity/diabetes are diverse." (PMID 36358953, 2022). "Overall, our findings therefore provide further support for the potential of OXT in therapeutic interventions for autism through shifting attention more towards social stimuli." (PMID 32398642, 2020). "For example, low levels of OXT in the brain are related to depression, schizophrenia, pain, and autism and OXT treatment targeting both the central and peripheral systems has been shown to help ameliorate some of these conditions." (PMID 31912136, 2020). "Deficits in OXT-immunoreactive (OXT-ir) neurons and peptide levels were observed in several monogenic mouse models of autism, including BTBR mice, CNTNAP2 KO mice and MAGEL2 KO mice." (PMID 30356897, 2018). "In several models of monogenic or multigenic heritable forms of autism, central OXT levels were also reported to be dysregulated." (PMID 30356897, 2018). "In the present study, the VPA-induced rat model of autism was used to investigate the relationship between its behavioral phenotype and the content of central OXT system in the brain." (PMID 30356897, 2018). "OXT signaling has been also implicated in bone maintenance, reduction of obesity in addition to its better-known role in formation of trust and bonding, and enhancement of OXT signaling is used in clinical trials for combating autism and age-related dementia." (PMID 28506310, 2017). "In particular, we focused on alterations in the expression of brain OXTRs because they are the target of intranasally administered OXT, a promising new treatment for social deficits in autism." (PMID 25225634, 2014). "Blood samples for sex hormone analysis were collected from 108 mothers (61 in autism, 47 in control group), of which 86 samples (40 in autism, 26 in control group) were tested for OXT and AVP concentrations." (PMID 24086383, 2013). "Resolving this dilemma becomes especially important with the increased momentum to understand a potential therapeutic role for OXT in autism spectrum and other neurodevelopmental disorders." (PMID 24376405, 2013). "In line with these understandings, OXT is currently under clinical trials for diseases such as autism, anxiety disorder, depression, drug abuse, and schizophrenia." (PMID 23700406, 2013). "Previous studies reported associations between OXT and OXTR genetic polymorphisms and risk for disorders characterized by impaired socio-emotional functioning, such as schizophrenia and autism." (PMID 23284802, 2012). "For instance, since the VP is part of the mesolimbic reward pathway, a reduced ability of OXT to activate OXTR in that area may contribute to a reduced experience of social reward or social motivation in autism." (PMID 41255981, 2025). "The newest studies on the central OXT system in VPA-induced rat models of autism confirm this hypothesis." (PMID 37888815, 2024). "Nevertheless, it remains unclear whether there is an involvement of the hippocampus and OXT in autism-like social cognitive impairments due to eIF4E overexpression." (PMID 39557567, 2024). "Furthermore, a study from Ben Ari group suggested that OXT or a selective NKCC1 inhibitor (bumetanide) at birth rescued the behavioral dysfunctions in two animal models of autism that showed deficits in the GABA switch." (PMID 37153633, 2023). "From earlier studies, the positive relationship between OXT and formation of social bonds in animals, which led to speculate that its abnormalities may be involved in autism, has been shown." (PMID 36358953, 2022). "The plasticity of the OXT system and its (patho)physiological significance were also previously reported in a study showing the parallel rescue of the OXT response and social behavior in a mouse model of autism." (PMID 36337662, 2022).
autism (continued). "Although the in vivo research for the OXT use in autism is mainly performed in rodents, notably genetically engineered mice, the equivalent research for OXT in obesity is performed in rodents, mainly rats, but also in other species, including non-human primates." (PMID 36358953, 2022). "Indeed, some clinical studies reported oxytocin receptor epigenetic variations or modifications in the circulating levels of OXT in individuals affected by autism and conduct disorders." (PMID 34068684, 2021). "Administration of OXT is reported to improve social recognition deficits in mouse models of autism." (PMID 34035071, 2021). "Given that some disorders are characterized by an imbalance between top‐down and bottom‐up threat processing, including anxiety disorders, schizophrenia, and autism, OXT may have a beneficial therapeutic effect in these disorders." (PMID 32832361, 2020). "The prosocial effects of OXT have been observed in genetically and phenotypically diverse mouse models of autism-relevant behaviors, leading to the belief that OXT could have generalized efficacy across subtypes of autism spectrum disorders." (PMID 32438751, 2020). "As primary outcomes, serum OXT levels will be assayed and social behaviors will be assessed via the Autism Behavior Checklist and the Social Responsiveness Scale which are validated questionnaires, an objective emotional facial matching test, and a new video-based eye-tracking test." (PMID 32082606, 2020). "This long-lasting improvement of postnatal OXT intervention on social behavior and OXT-ir neurons has also been observed in prairie voles, mandarin voles, mice, and monogenic mouse models of autism." (PMID 30356897, 2018). "Indeed, we find that differentially expressed genes in OXT neurons overlap with both mouse and human genes that have been implicated in ASD by the Simons Foundation Autism Research Initiative." (PMID 30192229, 2018). "Finally, we have shown that both behavioral and neural effects of OXT are modified to some extent by trait autism scores, although behavioral and functional connectivity effects were strongest in individuals with lower scores." (PMID 30108475, 2018). "OXT is emerging as a key neurochemical in both autism and obesity pathogenesis." (PMID 28859103, 2017). "These experiments in conjunction with the irregularities observed in the oxytocinergic system in autism make it plausible that OXT might in part modulate the brain rhythms in language-processing." (PMID 27378840, 2016). "That is, while lower mean plasma OXT levels were found in 6- to 11-year-old boys with autism compared to age matched healthy controls, elevated OXT levels were associated with lower scores on the Vineland Adaptive Behaviour Scale (VABS), which was reverse in the control group." (PMID 27256356, 2016). "Taken together, we can infer that altered sensory inputs in early life may be a potential etiological factor of autism, and if so, OXT may be considered a crucial regulator in this scenario." (PMID 27964753, 2016). "Our own literature search (PubMed, Google Scholar, until May 30th 2016) revealed that since this initial meta-analysis on OXT effects in autism, eight further studies have been published that investigated OXT effects on ASD patients." (PMID 27655235, 2016). "The role of OXT has well been established in social, maternal and sexual behaviors, and dysfunction of OXT system has been considered to be a factor in the etiology of autism." (PMID 27964753, 2016). "The overlapping distributions of the two neuropeptides, as revealed by other studies in autistic children, remind us that multiple factors contribute to the development of autism and a simple deficit of OXT or AVP is far from enough to interpret the etiology of this highly heterogeneous illness." (PMID 24086383, 2013). "In humans, autism is an exemplary disease, largely due to the insufficiency of OXT or OXT actions." (PMID 24967304, 2013).